AR (androgen receptor)
Diseases named in the same sentence as AR in open-access papers (continued):
Sharing a sentence is not in itself a finding about the gene and the disease.
prostate carcinoma (continued). "Silencing SNCG in a prostate cancer cell line has shown to decrease proliferation and invasion in vitro, and tumor growth in vivo, with the exception of castrated mice, suggesting AR-dependence." (PMID 31238876, 2019). "Together with other proteins called co-factors, the androgen receptor binds to DNA and switches on a set of target genes that drive the growth of prostate cancers." (PMID 30644358, 2019). "Many coregulators of hormonal receptor have been identified and Src homology 3 domain containing, Ysc84-like 1 (SH3YL1) is a novel coregulator that bind to the polyproline domain of androgen receptor (AR) in prostate cancer cell." (PMID 30813939, 2019). "Concordantly, the expression of LBCS and AR protein was negatively correlated in prostate cancer specimen (P = 0.002, R = − 0.676)." (PMID 31221168, 2019). "Therapeutic approaches that solely target androgen/AR signaling are insufficient to control prostate cancer cell activity." (PMID 30871130, 2019). "Androgen deprivation therapy can suppress hormone-naïve prostate cancers, but prostate cancer cells undergo various types of adaptive changes of AR and acquire the capacity to survive under castration levels of androgens." (PMID 31366128, 2019). "The role of androgen receptor (AR) in prostate cancer is one of the most well characterized examples." (PMID 30838415, 2019). "Given the prevalence of alterations in androgen signaling in human prostate cancers, we generated R26hARL/wt:p16L/L:PB-Cre4 compound mice, in which conditional AR expression and p16Ink4a deletion co-occur in prostate epithelium." (PMID 30677079, 2019). "Recent studies have demonstrated that stromal-cell-derived factors phosphorylate AR Ser-81 and regulate the proliferation of prostate cancer by activating the ERK pathway." (PMID 31395805, 2019). "Because PTEN is most commonly deleted tumor suppressor gene and AR is the most important therapeutic target in prostate cancer, these studies established the therapeutic importance of dissecting the relevant pathways." (PMID 30773595, 2019). "Concerning prostate cancer, the androgen receptor (AR) is majorly involved in tumorigenesis, while CDK5 can phosphorylate AR and promotes the proliferation of prostate cancer cells." (PMID 31395805, 2019). "Prostate cancer is driven by the AR signalling pathway, and an important treatment consists of androgen depletion, e.g., by castration." (PMID 30733525, 2019). "This study provides a strong preclinical rationale for developing therapeutic strategies to target antiapoptotic BCL2 signaling in combination with AR antagonists to improve treatment options for patients with advanced prostate cancer." (PMID 31228231, 2019). "Collectively, these results suggested that PSF functions as the “commander” of splicing machinery for prostate cancer progression and the AR." (PMID 30939845, 2019). "Genomic amplification of the androgen receptor (AR) is an established mechanism of antiandrogen resistance in prostate cancer." (PMID 30644358, 2019). "Findings in this study provide additional evidence for a tumor suppressor activity of ZFHX3 in AR-positive prostate cancer cells, as indicated by assays of SRB, colony formation in soft agar, and sphere formation in Matrigel." (PMID 30979864, 2019). "Aberrant androgen signaling drives prostate cancer and is targeted by drugs that diminish androgen production or impede androgen–androgen receptor (AR) interaction." (PMID 31431473, 2019). "This paradoxically toxic effect of androgen receptor agonists have been reported in another castration resistant prostate cancer model." (PMID 31552418, 2019). "Previous findings have shown a correlation between AR and human epidermal growth factor receptor 2 (Her2) in androgen-dependent prostate cancer cells, and Her2/ErbB3 activation stabilizes AR protein." (PMID 31395805, 2019).
prostate carcinoma (continued). "Experimental models support the idea that AR mediates, in part, the complex molecular interaction between CAFs and prostate cancer." (PMID 30832393, 2019). "In untreated primary prostate cancer AR gene amplification is low, while 50–85% of CRPCs have an increased AR copy number." (PMID 31366128, 2019). "A number of studies have proposed a correlation between microRNAs (miRNAs), a class of gene expression modulators, and AR in prostate cancer (PC), but there are still few evidences about the relationship between miRNAs and AR in BC." (PMID 30941159, 2019). "Concurrent inhibition of PI3K and AR in prostate cancer models has been shown to improve responses compared to either single agent alone." (PMID 34926721, 2019). "In summary, IRC117539 acts as an AR antagonist, which impairs AR-driven proliferation and survival of AR-positive prostate cancer cells in vitro." (PMID 31431473, 2019). "Another study showed that two glutamine transporters—SCL1A4 and SCL1A5—whose expression is stimulated by AR, are overexpressed in prostate cancer cells and stimulate glutamine uptake by these tumor cells and are required for maximal AR-driven proliferation." (PMID 31366128, 2019). "In the context of prostate cancer, the androgen receptor (AR) antagonist enzalutamide can become an agonist in the presence of a single mutation in the receptor—which is characteristic of resistance against this drug." (PMID 31500395, 2019). "Bromodomain (BRD) and extra-terminal motif (BET) protein inhibitors have been shown to attenuate AR signaling in metastatic castration-resistant prostate cancer and to overcome enzalutamide resistance." (PMID 31527644, 2019). "Current therapies for prostate cancer preferentially target proliferating, partially differentiated, and AR-dependent cancer cells that constitute the bulk of the tumor mass." (PMID 31143708, 2019). "In PTEN-/- prostate cancers, loss of NKX3.1 expression is mediated at the transcriptional level through the 11-kb region, despite functional androgen receptor is present in the nucleus of these cells." (PMID 31366128, 2019). "Here, the authors develop high resolution chromatin interaction maps in prostate cancer cells using in situ Hi-C, revealing prostate cancer-specific TADs and enhancer-promoter loops surrounding the androgen receptor (AR) locus." (PMID 31515496, 2019). "Significant overlap between AR and GR cistromes and transcription programs in prostate cancer cells was also described by others." (PMID 31855178, 2019). "Comparable observations were reported in prostate cancer, in which AR chromatin binding signatures were indicative of patient outcome." (PMID 30620009, 2019). "Prostate cancer (PCa) proliferation is fueled by activation of the androgen receptor (AR)‐signaling pathway." (PMID 30776192, 2019). "Our results thus provide a structural basis for how chaperones manage the stability, activation, solubility and turnover of AR, which should inform efforts to treat both prostate cancer and SBMA." (PMID 31395886, 2019). "The androgen receptor plays key roles in the development of prostate tissue; however, an ‘AR malignancy shift’ (AMS) can occur which allows AR to also drive prostate cancer (PC)." (PMID 31520575, 2019). "ChIP assay on DHT-treated LNCaP prostate cancer cells showed a dynamic interaction of AR with the promoter and enhancer, where AR loaded onto enhancers to a greater extent, but enhancer association was more transient than that to the promoter." (PMID 31275057, 2019). "IL-8 signaling has been implicated in regulating the transcriptional activity of the androgen receptor, underpinning the transition to an androgen-independent proliferation of prostate cancer cells." (PMID 31488216, 2019). "Genomic approaches in prostate cancer (PCa) have identified that the signaling capacity of the androgen receptor (AR) becomes skewed with disease progression." (PMID 30120411, 2019).
prostate carcinoma (continued). "AR signaling is one of the major growth promoting pathways in prostate cancer, and ADT is the corner stone of prostate cancer treatment." (PMID 31357527, 2019). "In this paper, we review the literature on the role of AR detected in the plasma of patients with prostate cancer as a novel prognostic and predictive biomarker in different settings of prostate cancer." (PMID 31689899, 2019). "Collectively, these data implicate GREB1 as an AR signal amplifier that contributes to prostate cancer disease progression and antiandrogen resistance." (PMID 30644358, 2019). "In prostate cancer, androgen receptor signalling is a significant pathway for the cancer progression." (PMID 30887697, 2019). "Olaparib treatment reduced AR levels only in BRCA2-knockdown prostate cancer cells, indicating that 6-TG and olaparib regulate AR through different molecular mechanisms, the first being BRCA2-independent and the second BRCA2-dependent." (PMID 31284411, 2019). "In fact, it was demonstrated the ability of AR to enhance invasion of prostate cancer cell lines, independently of its nuclear localization but in a Src-dependent manner." (PMID 30832393, 2019). "Such an association is mind-boggling given that androgen deprivation therapy, which aims to suppress AR signaling in tumor cells, often serves as the frontline treatment of prostate cancer." (PMID 30925918, 2019). "Genetic alterations of AR frequently occur during the course of prostate cancer initiation and progression in the presence of other genetic and epigenetic changes." (PMID 30677079, 2019). "Using a panel of Enzalutamide-resistant prostate cancer cell lines, these authors provided evidence that BET bromodomain inhibitors enhance efficacy and disrupt resistance to AR antagonists in the treatment of prostate cancer." (PMID 31366128, 2019). "Pharmacologic treatment of Stat5 is an efficient approach to delay castrate-resistant progression, due to the cooperation between Stat5 and Androgen Receptor to promote prostate cancer progression." (PMID 31366128, 2019). "The NR superfamily includes androgen receptor, which is a key player in prostate cancer pathogenesis, suggesting the functional roles of other NRs in prostate cancer." (PMID 31212954, 2019). "AR-negative prostate cancer cells are refractory to IRC117539, arguing that drug-induced AR loss initiates prostate cancer cell death." (PMID 31431473, 2019). "Several preclinical studies using prostate cancer models showed that curcumin modulated the androgen receptor signaling and downstream targets such as VEGF, PTEN, and NF-κB." (PMID 31581661, 2019). "Another previously reported mechanism of AR nuclear export that we examined in our cell models is the CRM1-dependent nuclear export of AR that occurs in several prostate cancer cell lines upon inhibition of GSK-3β29,30,65." (PMID 30644418, 2019). "Research has shown that dihydrotestosterone (DHT) can upregulate SGK3 expression via androgen receptor (AR) and promote the proliferation of prostate cancer cells." (PMID 30108027, 2019). "It has been reported that increased AR activity drives therapeutic resistance in advanced prostate cancer." (PMID 31295943, 2019). "Androgen stimulation of androgen-dependent and castration-resistant prostate cancer cell lines results in upregulation of CaMKKβ, indicating direct regulation by the androgen receptor." (PMID 30621060, 2019). "AR antagonists induce telomere DNA damage in AR-positive LNCaP prostate cancer cells, and a DDR that has the features of a bona fide telomere DDR, namely, activation of ATM, as indicated by an increase in phosphorylated ATM (pATM) at telomeres." (PMID 31083651, 2019). "This review focuses on such suppressive effects of androgen/AR signaling on prostate cancer cells through CCL-CCR axes." (PMID 30871130, 2019). "The bipartite AR/Src complex controls prostatic cancer cell proliferation in vitro or in nude mice xenografts." (PMID 30872694, 2019).
prostate carcinoma (continued). "In summary, the ability to determine key resistance-mediating AR modifications in CTCs has the potential to considerably improve prostate cancer treatment." (PMID 31289619, 2019). "Lnc-LBCS functions as a novel AR translational regulator that suppresses castration resistance of prostate cancer by interacting with hnRNPK." (PMID 31221168, 2019). "Transition of prostate cancer to the castration-resistant phenotype correlates with accumulation of a splice isoform of AR called AR-V7, that acts as a constitutively active transcription factor." (PMID 30832393, 2019). "Whole genome sequencing of 11 early onset prostate cancers suggested that androgens, through AR, contribute in shaping somatic alterations." (PMID 31328183, 2018). "We observed comparable competitive behaviour using an alternative AR-positive prostate cancer cell line, LNCaP, and determined a Ki value for the Enzalutamide-AR interaction within LNCaP cells in a similar range to the one measured in CWR22Pc-R1-AD1 cells." (PMID 29317749, 2018). "One class of the drugs works by binding to and inactivating the androgen receptor protein on prostate cancer cells." (PMID 29334357, 2018). "The anti-prostate cancer effect of W. chinensis extracts is ascribed to three active compounds: wedelolactone, luteolin, and apigenin, which inhibit the androgen receptor (AR) signaling pathway in LNCaP and 22Rv1 cells." (PMID 29495626, 2018). "AR is the central oncogenic driver of prostate cancer (PCa) and is also a key regulator of DNA repair in cancer." (PMID 29691406, 2018). "Previous study has revealed that endothelial cells promoted invasion of prostate cancer cells by suppressing AR signaling." (PMID 30200999, 2018). "In summary, our findings have demonstrated for the first time that the cytoplasmic (non‐genomic) activity of HDAC3 is required for AKT phosphorylation and AR upregulation in prostate cancer cells." (PMID 29523594, 2018). "AR-mediated signalling works paradoxically in breast cancer and prostate cancer, and cancer cells expressing the AR are endocrine-sensitive." (PMID 30577860, 2018). "For most of our experiments the AR-negative PC3 prostate cancer cell line was used so that, of the cells in co-culture, only the myofibroblasts expressed AR." (PMID 29721186, 2018). "FOXA1 is an AR transcription factor that promotes prostatic cancer oncogenesis and progression mainly by increasing the transcriptional activity of AR." (PMID 29581876, 2018). "The increased expression of MAGE-11 facilitates prostate cancer progression by enhancing AR-dependent tumor growth." (PMID 30185218, 2018). "The androgen receptor is a major driver of prostate cancer and inhibition of its transcriptional activity using competitive antagonists, such as enzalutamide remains a frontline therapy for prostate cancer management." (PMID 30271980, 2018). "- TMPRSS2-ERG gene fusion leads to ETS-related gene (ERG) and steroidogenic enzyme AKR1C3 co-overexpression which promotes AR signaling and represents a promising target in prostate cancer." (PMID 30319966, 2018). "Loss of Rb during cancer progression correlated with increased levels of “free” E2F1 and androgen receptor (AR) levels in patients with castrate-resistant prostate cancer metastases." (PMID 30279956, 2018). "Taken together with our observations, these data suggest a compensatory relationship between AR and estrogen signaling in both prostate cancer and triple negative breast cancers." (PMID 30314329, 2018). "This pathway can be used to modulate AR expression and eventually lead to the development of novel therapeutic tools for prostate cancer." (PMID 29988966, 2018).
prostate carcinoma (continued). "This discovery conceptually advances our understanding of a novel, PRC1-independent role of BMI1 in prostate cancer progression through the AR pathway." (PMID 29402932, 2018). "Consistent with the literature, treating LNCaP cells with MDV3100 or culturing another AR-positive prostate cancer cell line 22Rv1 in CSS medium has resulted in induction of H3K27me3 and NE markers, which suggests that ADT activates EZH2’s PRC2 activity." (PMID 30287808, 2018). "LIMK1 enhances nuclear androgen receptor translocation, leading to prostate cancer cell proliferation and survival." (PMID 29970879, 2018). "AR stimulation increases IGF1R expression in prostate cancer cells and hexosamine production, resulting in increased N- and O-glycosylation." (PMID 29462882, 2018). "We further describe the role of NF-κB in prostate cancer cell survival and proliferation, major NF-κB signaling pathways in prostate cancer, and the crosstalk between NF-κB and androgen receptor signaling." (PMID 30158439, 2018). "Prostate cancer progression is known to be regulated by androgen/androgen receptor (AR) signaling pathway." (PMID 30177619, 2018). "The metastatic castration-resistant prostate cancer (CRPC) is a lethal form of prostate cancer, in which the expression of androgen receptor (AR) is highly heterogeneous." (PMID 29555975, 2018). "This special issue of Cancers initially reviews the role of AR in advanced prostate cancer, and then explores the potential importance of AR signaling in other epithelial malignancies." (PMID 29346310, 2018). "Oxidative stress, inflammation and androgen receptor (AR) signaling play a pivotal role in the initiation, development and progression of prostate cancer (PCa)." (PMID 30257470, 2018). "It is clear that AR signaling plays a critical role in the development and progression of prostate cancer and serves as a central component of progression to CRPC." (PMID 31328183, 2018). "For example, curcumin interrupts the interaction between the androgen receptor (AR) and Wnt/β-catenin signaling pathway in LNCaP prostate cancer cells." (PMID 29636777, 2018). "Hormone induced double strand breaks upon binding of the Androgen Receptor (AR) has been involved in such processes in prostate cancers." (PMID 29360755, 2018). "For example, three SRAP isoforms are expressed in human prostate cell lines, and transfection of SRAP-coding SRAs promotes AR transcriptional activity in several prostate cancer cells (such as PC-3, DU-145, and LNCaP cells)." (PMID 30238005, 2018). "Our study revealed that the TLX-induced resistance to androgen deprivation and anti-androgen was mediated through its direct suppression of AR gene transcription and signaling in both androgen-stimulated and -unstimulated prostate cancer cells." (PMID 29555975, 2018). "The AR belongs to the nuclear receptor superfamily of transcription factors, and is essential for prostate cancer cell survival, proliferation and invasion." (PMID 30271587, 2018). "In androgen-dependent prostate cancer cells, AR depletion or anti-androgen therapy induce features of survival factor deprivation, such as cell cycle arrest and apoptosis." (PMID 29371637, 2018). "These different isoform preferences of CDK5 between androgen-independent or dependent prostate cancer cell lines implies that CDK5 can modulate AR transcriptional activity through differential splicing in accordance with the present or absent of androgen." (PMID 30367578, 2018). "The isoform ratio change of CDK5 can act as a fine tuner of AR activity and contribute to prostate cancer progression." (PMID 30367578, 2018). "Although AR-regulated signaling pathways are well established in prostate cancer, the involvement of AR in GBM and the potential AR-dependent or independent regulated signaling pathway in GBM is not known." (PMID 29731997, 2018).